SH2B1 (SH2B adaptor protein 1)
Diseases named in the same sentence as SH2B1 in open-access papers (continued):
Sharing a sentence is not in itself a finding about the gene and the disease.
Obesity (continued). "Conversely, overexpression of SH2B1 in either total or DRN‐projecting PVHSH2B1 neurons protected against HFD‐induced obesity, metabolic disorders, and MASLD." (PMID 38885417, 2024). "There is little evidence for haploinsufficiency (HI score:1) recorded in ClinGen database for SH2B1 gene, including developmental delay, severe obesity, hyperphagia and insulin resistance." (PMID 39039444, 2024). "Both embryonic‐onset and adult‐onset deletion of Sh2b1 in PVH neurons caused hyperphagia, reduced energy expenditure, obesity, insulin resistance, glucose intolerance, and MASLD." (PMID 38885417, 2024). "In conclusion, these results unveil a previously unrecognized PVHSH2B1→DRN neurocircuit through which SH2B1 defends against obesity by enhancing BDNF/TrkB signaling." (PMID 38885417, 2024). "Ablation of Sh2b1 in the DRN‐projecting PVHSH2B1 subpopulation also causes energy imbalance, obesity, and metabolic disorders." (PMID 38885417, 2024). "Neuron‐specific restoration of SH2B1 rescues the obesity phenotype of Sh2b1‐null mice, indicating that the brain is a main SH2B1 target." (PMID 38885417, 2024). "In male and female mice, either embryonic‐onset or adult‐onset deletion of Sh2b1 in PVH neurons causes energy imbalance, obesity, insulin resistance, glucose intolerance, and MASLD." (PMID 38885417, 2024). "Conversely, SH2B1 overexpression in either total or DRN‐projecting PVHSH2B1 neurons protects against diet‐induced obesity." (PMID 38885417, 2024). "Collectively, these results suggest that PVHSH2B1 neuron‐intrinsic SH2B1 protects against energy imbalance and obesity at least in part by enhancing BDNF/TrkB pathways in the PVH." (PMID 38885417, 2024). "demonstrate that people carrying a deletion on chromosome 16p11.2 containing the SH2B1 gene have early-onset obesity and difficult-to-treat type 2 diabetes." (PMID 37586323, 2023). "SH2B1, which belongs to the family of SH2-domain containing mediators, has previously been associated with severe early-onset obesity and has been shown to influence human intelligence." (PMID 38434247, 2023). "In a study of 25 obese Guadeloupean patients, 5 heterozygous variants in 4 monogenic obesity genes (MC4R, NTRK2, SH2B1, and SIM1) were detected with a prevalence of 10%." (PMID 37329217, 2023). "In terms of metabolic control in specific tissues and cell types, Sh2B1’s expression in both central nervous system neurons and peripheral non-neuronal cells is crucial for protection against obesity and metabolic diseases." (PMID 38434247, 2023). "Sh2b1 knockout mice develop obesity, hyperglycemia, hepatic steatosis, and lipid accumulation in skeletal muscle." (PMID 37586323, 2023). "To explore the potential involvement of obesity in the SH2B1-mediated regulation of FI, we performed additional analyses focusing specifically on normal weight individuals (n = 109,457) from the UKBB cohort." (PMID 38434247, 2023). "Conversely, overexpressing SH2B1 enhances leptin sensitivity, suggesting its potential as a therapeutic target for obesity." (PMID 38027481, 2023). "Eight cases exhibited obesity, and this region contains the SH2B1 gene, the deletion of which can lead to obesity in humans." (PMID 36553582, 2022). "Of the identified genes in our study, FTO, GNPDA2, MC4R, MTCH2, NEGR1, SH2B1, TMEM18 are unequivocally regarded as obesity genes associated with PCOS, as supported by contemporary evidence." (PMID 35679284, 2022). "The 6p11.2 distal deletion includes the SH2B1 gene involved in leptin and insulin signalling and has been shown to have a polymorphic effect on obesity." (PMID 35590413, 2022). "SH2B1 is a well-known metabolic regulator related to obesity and liver lipid metabolism, and rs7498665 is associated with visceral fat." (PMID 34635168, 2021). "The expression level of each of the five obesity-related genes (SH2B1, GNPDA2, FTO, TMEM18, and KCTD15) in three cancer tissues (HNSC, LIHC, and CHOL) was higher than that in the corresponding normal tissues." (PMID 33299884, 2020).
Obesity (continued). "In conclusion, we unravel an unrecognized LepR neuron Sh2b1/SNS/adipose energy expenditure axis that combats against obesity, type 2 diabetes, and NAFLD." (PMID 32251290, 2020). "We herein identify LepR neurons as key Sh2b1 targets that mediate Sh2b1 protection against obesity, type 2 diabetes, and NAFLD." (PMID 32251290, 2020). "Sh2b1ΔLepR mice, like global Sh2b1 knockout mice, develop obesity, insulin resistance, and liver steatosis." (PMID 32251290, 2020). "Mice with either LepR neuron-specific or adult-onset, hypothalamus-specific ablation of Sh2b1 develop obesity, insulin resistance, and liver steatosis." (PMID 32251290, 2020). "In contrast, hypothalamic overexpression of SH2B1 protects against high fat diet-induced obesity and metabolic syndromes." (PMID 32251290, 2020). "We demonstrated that LepR neuron-specific deletion of Sh2b1, or adult-onset deletion of Sh2b1 in the hypothalamus (containing LepR neurons), resulted in severe obesity, insulin resistance, and liver steatosis." (PMID 32251290, 2020). "In this sense, scientific evidence revealed that SH2B1 knock-out mice develop obesity and hyperglycemia, hyperinsulinemia, glucose intolerance and insulin resistance due to the central role of SH2B1 in the regulation of glucose and lipid metabolism." (PMID 32365683, 2020). "For three types of cancer (LUSC, BLCA, and LUAD), history of smoking and expression levels of three obesity-related genes (SH2B1, POMC, and KCTD15) influenced the survival probability of patients with LUSC." (PMID 33299884, 2020). "Together, these data suggest that POMC neuron-specific ablation of Sh2b1 is insufficient to induce obesity and metabolic disease." (PMID 32251290, 2020). "Collectively, our results unveil an unrecognized leptin/Sh2b1/sympathetic nerve/adipose thermogenesis axis that combats obesity, type 2 diabetes, and liver steatosis." (PMID 32251290, 2020). "Our results unravel an unrecognized LepR neuron Sh2b1/SNS/BAT/thermogenesis axis that combats obesity and metabolic disease." (PMID 32251290, 2020). "Associations of the loci SH2B1 (rs7498665), near GNPDA2 (rs10938397), MTCH2 (rs10838738), and near MC4R (rs12970134) with obesity have been shown in many studies." (PMID 32228543, 2020). "Several obesity susceptibility loci in genes, including GNPDA2, SH2B1, TMEM18, MTCH2, CDKAL1, FAIM2, and MC4R, have been identified by genome-wide association studies." (PMID 32228543, 2020). "Conversely, MBH-specific overexpression of SH2B1 ameliorated HFD-induced obesity and metabolic syndromes." (PMID 32251290, 2020). "For example, obesity risk alleles in MC4R were shown to be associated with an increased caloric intake and a higher percentage of calories from fat; SH2B1 obesity risk alleles were linked to increased fat intake." (PMID 32228543, 2020). "Other genes are involved in the melanocortin signalling pathway and many of these have also been implicated in monogenic forms of obesity, including POMC, PCSK, SIM1, BDNF, NTRK2, SH2B1 and MRAP." (PMID 31488071, 2019). "Previous study in mice have shown that expression of Sh2b1 on the mRNA level in obesity mice was decreased, which resulted in significant reduction in male fertility and exacerbated reproductive toxicity and germ cell mutagenicity." (PMID 31666004, 2019). "The locus chr16:28719857 (p-value 4.36 × 10− 6) contains genes associated with body fat percentage (APOBR) and BMI (SH2B1), and rs12154393 (p-value 3.06 × 10–6) contains THSD7A, a candidate gene for obesity." (PMID 31533690, 2019). "Deletion of the SH2B1 gene in mice has been shown to result in a severe leptin resistance, obesity, insulin resistance, and T2D, demonstrating its critical role for the maintenance of normal body weight, insulin sensitivity, and glucose metabolism." (PMID 30651891, 2019).
Obesity (continued). "Our findings implicate many genes previously associated with obesity (e.g. PTBP2, TMEM18, MYT1L, POU3F2, SIM1, SH2B1), and also identified other potentially relevant candidates including TAS1R3, ALOX5AP, and GAS6." (PMID 29441128, 2018). "In clinical disease, the research of SH2B1 mainly focused on energy imbalance, severe leptin resistance, obesity and type 2 diabetes." (PMID 30202243, 2018). "In sum, of the five analyzed genes SH2B1 and APOBR comprised non-synonymous variants associated with obesity." (PMID 25955518, 2015). "This was important for highlighting the role of the CNS in the development of obesity, since SH2B1 is expressed both in the CNS and peripheral tissues." (PMID 26715945, 2015). "We have previously reported rare variants in sarcoma (Src) homology 2 (SH2) B adaptor protein 1 (SH2B1) in individuals with obesity, insulin resistance, and maladaptive behavior." (PMID 24971614, 2014). "Our results identified significant associations between 2 polymorphisms (SH2B1 rs7498665 and FAIM2 rs7138803) and overweight/obesity." (PMID 24621099, 2014). "This study highlighted the importance of above two candidate genes (SH2B1 and FAIM2) in the risk of overweight/obesity." (PMID 24621099, 2014). "This locus includes the SH2B adaptor protein 1 (SH2B1) gene, which is likely responsible for obesity in these individuals." (PMID 25411582, 2014). "Our meta-analyses have shown the important role of 2 polymorphisms (SH2B1 rs7498665 and FAIM2 rs7138803) in the development of overweight/obesity." (PMID 24621099, 2014). "Sanger sequencing of PCR products of all FTO and SH2B1 exons and their flanking regions were performed in 338 Chinese Han children with obesity and 221 age- and sex-matched lean controls." (PMID 23825611, 2013). "Other loci, including the INSIG2, TMEM18, KCTD15, SH2B1, MTCH2, GNPDA2, BDNF, or CHST8 genes, have also been associated with obesity." (PMID 24267414, 2013). "We previously reported that neuron-specific restoration of SH2B1β transgenes (Tg) into SH2B1 knockout (KO) mice (called TgKO mice) fully corrects leptin resistance, hyperphagia, and obesity in TgKO mice." (PMID 24358267, 2013). "Genetic disruption of the SH2B1 gene results in severe leptin resistance, insulin resistance, obesity, type 2 diabetes, and NAFLD in mice." (PMID 24358267, 2013). "SH2B1 directly enhances leptin signaling in cultured cells; therefore, neuronal SH2B1 exerts anti-obesity action at least in part by enhancing leptin sensitivity." (PMID 24358267, 2013). "We initially detected transmission disequilibrium for a SNP in the vicinity of SH2B1 (rs2008514) in 705 obesity trios (p =0.0094 of TDT)." (PMID 23270367, 2012). "Other signals near BDNF, SH2B1, and NEGR1 (all implicated in aspects of neuronal function) reinforce the view of obesity as a disorder of hypothalamic function." (PMID 22474595, 2012). "With regard to animal models, Sh2b1 null mice show a phenotype of obesity, hyperlipidemia, leptin resistance, hyperphagia, hyperglycaemia, insulin resistance and glucose intolerance." (PMID 23270367, 2012). "Deletion of the SH2B1 gene resulted in metabolic disorders in SH2B1 knockout mice, including hyperlipidemia, leptin resistance, hyperphagia, obesity, hyperglycemia, insulin resistance, and glucose intolerance." (PMID 22474595, 2012). "Deletions on chromosome 16p11.2 have been reported in an adult population with severe obesity, further demonstrating the potential importance in SH2B1 gene variation and the development of human obesity." (PMID 22474595, 2012). "Recently, analysis of GWAS-derived obesity gene variants provided evidence of positive natural selection at the FTO, NEGR1, SH2B1 and FAIM2 loci." (PMID 22043165, 2011). "The SH2B adapter protein 1 (SH2B1) is one of these genes and is an excellent candidate gene to link the 16p11.2 deletion to obesity." (PMID 22043164, 2011).
Obesity (continued). "It was reported that SH2B1 null mice rapidly increase their body mass and develop obesity as a result of significantly impaired hypothalamic leptin signaling resulting in hyperleptinemia and hyperphagia." (PMID 20333234, 2010). "Other studies have shown that SH2B1 null mice actually increase their body mass and develop obesity as a result of hyperphagia." (PMID 20333234, 2010). "Recently, deletions in the region p11.2 of the chromosome 16 encompassing the gene SH2B1, which is involved in the leptin and insulin signaling, have been reported in about 0.5% of children with severe early-onset obesity." (PMID 20540750, 2010). "These pathways regulate food intake and energy expenditure, linking SH2B1 to obesity development." (PMID 40077044, 2025). "Additionally, in a study of 25 patients with obesity from Guadeloupe, five heterozygous variants were identified in the MC4R, NTRK2, SH2B1, and SIM1 genes, with a frequency of approximately 10%." (PMID 40149731, 2025). "Importantly, restoring neuronal SH2B1 in SH2B1 knockout mice rescued hyperphagia and obesity and protected from diet-induced weight gain and insulin resistance, indicating that neuronal SH2B1 is essential for controlling energy and glucose homeostasis." (PMID 41251447, 2025). "Therefore, the results are likely mediated by the direct interaction of miR-361 with the SH2B1 (SH2B adaptor protein 1) gene, which is linked to obesity and appears to be affected by the quality of dietary macronutrients." (PMID 40149500, 2025). "Besides serving as an oncogene, SH2B1 also exerts crucial roles in energy homeostasis, obesity, and glucose metabolism." (PMID 41410190, 2025). "Likewise, deletion of Sh2b1 in DRN‐projecting PVHSH2B1 neurons, using the Cre‐dependent, Flp‐dependent, and retrograde AAV paradigm, also caused energy imbalance, obesity, insulin resistance, and MASLD." (PMID 38885417, 2024). "SH2B1 counteracts energy imbalance and obesity at least in part by enhancing BDNF action." (PMID 38885417, 2024). "Global deletion of Sh2b1 results in severe obesity, type 2 diabetes, and MASLD in mice." (PMID 38885417, 2024). "SH2B1 mutant mice present hyperphagia, insulin resistance, and obesity, and hypothalamic overexpression of this protein increases leptin-signaling pathway activity that protects against high-fat-diet-induced obesity and metabolic syndromes." (PMID 36674935, 2023). "Its deletion provokes metabolic disorders in SH2B1 KO mice, including leptin resistance, obesity, and glucose intolerance whereas restoration of SH2B1 corrected these metabolic disturbances and improved JAK2-mediated leptin signaling and regulation of hypothalamic orexigenic neuropeptides." (PMID 36674935, 2023). "First, we confirmed in the UKBB database that SH2B1 is both an obesity susceptibility locus and a gene with an overlapping effect on FI in the same cohort, using records for GWAS on BMI and TFM, 2 anthropometric traits associated with obesity." (PMID 38434247, 2023). "Fifth, our analysis showed that the association between SH2B1 and intelligence remained significant even when normal weight individuals were analyzed, suggesting that obesity is not a prerequisite for the association between SH2B1 and FI." (PMID 38434247, 2023). "However, it is worth noting that hypothalamic overexpression of SH2B1 was recently reported in a mouse model to protect against obesity and metabolic disease, including diet-induced IR71." (PMID 34230558, 2021). "The Sh2b1/SNS/fat axis may serve as a potential therapeutic target for the treatment of obesity and metabolic disease." (PMID 32251290, 2020). "Sh2b1-null mice develop severe leptin resistance, obesity, and type 2 diabetes." (PMID 32251290, 2020). "Overall, these studies report that adherence to a Mediterranean Diet and/or calorie restriction were associated with decreased DNA methylation in obesity-related genes such as PDK4, KCNQ1, WT1, SH2B1, FTO, BDNF, and PPARGC1A or inflammatory genes such as TNF-α." (PMID 31506096, 2019).
Obesity (continued). "Particularly, the region harboring the SH2B1 gene was reported in early-onset obesity." (PMID 31379474, 2019). "The present study suggest that it may also be worthwhile to further explore how SH2B1 and related genes on neurotrophin signaling pathway affect ASD and risk of obesity in the ASD population." (PMID 31379474, 2019). "Furthermore, there is a greater incidence of obesity in the ASD population and SH2B1 is reported to be causative for obesity." (PMID 31379474, 2019). "SH2B1 enhances leptin signaling through the augmentation of JAK2 activity, and deletions or mutations in the SH2B1 gene are known to be associated with severe obesity in humans and mice." (PMID 28912580, 2017). "Moreover, the obesity observed in Sh2b1-null mice was reversed by the targeted expression of Sh2b1 in neurons." (PMID 26715945, 2015). "Many animal studies have shown that SH2B1 is involved in the development of obesity." (PMID 24621099, 2014). "SH2B1 is an enhancer that may influence the phenotype of obesity through JAK-STAT pathway, which is important in the development and function of adipocytes." (PMID 24621099, 2014). "Apart from those in FTO, several of the identified SNPs are located in or near genes clearly related to appetite regulation, and recently, five of the novel obesity loci (SH2B1, KCTD15, MTCH2, NEGR1 and BDNF) were indicated to be associated with dietary macronutrient intake levels." (PMID 23861046, 2013). "The rare missense mutations of FTO and SH2B1 did not confer risks of obesity in Chinese Han children in our cohort." (PMID 23825611, 2013). "Genetic deletion of SH2B1 results in obesity, type 2 diabetes, and fatty liver diseases in mice." (PMID 24358267, 2013). "SH2B1 knockout mice develop obesity, diabetes and insulin resistance." (PMID 24260264, 2013). "The rare missense mutations of FTO and SH2B1 do not confer risks of obesity in Chinese Han children in our cohort." (PMID 23825611, 2013). "Among the new discovered loci, ATXN2L, NEGR1 and SH2B1 have also shown a relationship with obesity." (PMID 24267414, 2013). "Together, these data indicate that hepatic SH2B1 promotes hepatic lipid accumulation in adult mice fed a HFD, which may contribute to obesity-associated NAFLD." (PMID 24358267, 2013). "In addition, 7 of the 17 (41.2%) GWAs-selected genes (FTO, TMEM18, INSIG2, FAIM2/BCDIN3, BDNF, SH2B1 and MC4R) were associated with obesity in this population." (PMID 23950976, 2013). "In addition, SH2B1 was associated only with class I/II obesity and MC4R only with class III obesity." (PMID 23950976, 2013). "Moreover, neuron-specific overexpression of SH2B1 dose-dependently protected against high-fat diet-induced leptin resistance and obesity." (PMID 22474595, 2012). "Evidence in humans and from animal models suggests that SH2B1 is a likely obesity gene." (PMID 23270367, 2012). "The SH2B1 gene (Src-homology 2B adaptor protein 1 gene) is a solid candidate gene for obesity." (PMID 23270367, 2012). "Indeed, SH2B1 modulates leptin sensitivity and Sh2b1 knock-out mice develop hyperphagia and obesity." (PMID 22043164, 2011). "Of the individual SNP analyses, only rs6548238 near TMEM18, rs10838738 in MTCH2, and rs7498665 near SH2B1 showed nominally significant interactions with physical activity level on BMI or obesity risk, but none survived adjustment for multiple comparisons." (PMID 20824172, 2010). "It's plausible to speculate that loss-of-function mutation of SH2B1 may not significantly involved in pathogenesis of Chinese children obesity." (PMID 23825611, 2013). "GWAS of SevO found numerous susceptibility loci that intersected with earlier-identified BMI loci including the archetypal FTO, MC4R, SH2B1 and NPC1 suggesting little etiological heterogeneity between obesity subgroups." (PMID 40939575, 2025). "Other critical modulators of the obesity phenotype exist within the ATP2A1 locus, such as SH2B1, a gene involved in leptin and insulin signaling." (PMID 34489471, 2021).